ENSG00000278852
Gene: Miscellaneous RNA gene on chromosome 1 (11,845,549 to 11,845,697, forward strand). Ensembl gene ENSG00000278852.
Gene Ontology:
Molecular function: mRNA binding
Biological process: regulation of gene expression